AR (androgen receptor)
Diseases named in the same sentence as AR in open-access papers (continued):
Sharing a sentence is not in itself a finding about the gene and the disease.
triple-negative breast carcinoma (continued). "Specifically speaking, seviteronel (a novel CYP17 inhibitor and AR antagonist) can enhance the sensitivity of AR-positive triple-negative breast cancer cells to radiotherapy with low side effects." (PMID 40868150, 2025). "In contrast, luminal androgen receptor–positive triple-negative breast cancer demonstrates a less aggressive phenotype with lower proliferation indices and better outcomes." (PMID 40373794, 2025). "In contrast, they account for less than 10% of triple-negative breast cancer, with the highest prevalence in the luminal androgen receptor subtype." (PMID 40002579, 2025). "A subset of triple-negative breast cancer (TNBC) expresses the androgen receptor (AR), but thresholds for AR positivity and its clinical significance vary." (PMID 39851328, 2025). "In fact, about 57% to 80% of triple-negative breast cancer (TNBC) lack AR expression (known as QNBC) and were shown to present more aggressive biological and clinical behavior." (PMID 40862714, 2025). "The authors identified a “high-risk” profile for triple-negative breast cancer (TNBC), characterized by low expression levels of PD-L1 and androgen receptor (AR), alongside high expression levels of epidermal growth factor receptor (EGFR) and Ki67." (PMID 39682581, 2024). "A significant proportion of Her2-positive and triple-negative breast cancer cases also show AR positivity." (PMID 39497884, 2024). "In a previous study, RUNX1 was found to collaborate with the androgen receptor in triple-negative breast cancer CSCs to promote cancer recurrence after chemotherapy, whereas inhibition of RUNX1 transcriptional activity reduced expression of CSC marker genes." (PMID 39107908, 2024). "We found that CREB3L4 is highly upregulated in a specific subtype of triple-negative breast cancer, the intraluminal androgen receptor (LAR) subtype, and can be used as a potential therapeutic target." (PMID 39254691, 2024). "For instance, AR suppresses GPER1 signaling to promote cell proliferation in triple-negative breast cancer." (PMID 39582864, 2024). "We discovered an overdrive of a FOXM1-mediated transcriptional signaling cascade in AR-low relative to AR-high triple-negative breast cancers (TNBCs)." (PMID 39335162, 2024). "The presence of estrogen receptor beta, the androgen receptor, and the glucocorticoid receptor on triple-negative breast cancer cells has opened the possibility for the development of new treatment approaches against this disease." (PMID 37835396, 2023). "The AR drives Luminal AR (LAR) triple-negative breast cancer progression, and LAR patients consistently exhibit positive clinical benefits with AR antagonists in clinical trials." (PMID 38203649, 2023). "Since androgen receptor positivity characterizes a molecular subtype of triple-negative breast cancer, we also performed staining for the androgen receptor." (PMID 36769215, 2023). "As most patients with triple-negative breast cancer (TNBC) (60–80%) exhibit mutations in BRCA1 and AR activity is directly influenced by BRCA1, AR can potentially be a prognostic marker for TNBC14." (PMID 36450882, 2022). "The literature aims to explore anti-androgenic particulars against luminal androgen receptor-specific triple-negative breast cancer, thus providing a concise report on the clinical profile of anti-androgens." (PMID 36612226, 2022). "In triple-negative breast cancers (TNBCs), the luminal AR subtype expresses high levels of AR and shows decreased relapse-free survival." (PMID 35207749, 2022). "Collectively, though morphologically and phenotypically distinct from PC, our data suggest that DSRCT is a second androgen-stimulated malignancy (third, if one considers the AR-positive molecular subset of triple-negative breast cancer)." (PMID 35650195, 2022).
triple-negative breast carcinoma (continued). "Recent studies have also found that luteolin significantly inhibits cancer cell proliferation and metastasis through the AKT/mTOR/MMP9 signaling pathway in androgen receptor-positive triple-negative breast cancer." (PMID 35678671, 2022). "It is probably due to the Luminal androgen receptor (LAR) subtype of triple-negative breast cancers (TNBCs), which is abundant in AR expression." (PMID 35800434, 2022). "AR levels have been reported as significant predictors of response to primary adjuvant endocrine therapy, but only under certain circumstances: either in triple negative breast cancer or when only specific genotypes of AR are considered." (PMID 36527133, 2022). "In our review, we aimed to identify clinical features and proposed potential therapeutic approaches of this specific subgroup—AR-positive triple-negative breast cancer." (PMID 33915941, 2021). "Yet, triple-negative breast cancers that lose AR expression often have characteristics of primitive basal-like cancers with poor clinical course." (PMID 34768683, 2021). "Based on a comprehensive gene expression analysis of an AR-positive, triple negative breast cancer patient-derived xenograft (PDX) model, 163 dihydrotestosterone (DHT)-responsive genes were defined as an androgen responsive gene set." (PMID 34736512, 2021). "The present study indicated the Bicalutamide inhibited the proliferation and invasion process of triple negative breast cancer cells by targeting AR signaling pathway and down-regulating MMP-2/-9 protein expression levels." (PMID 32332626, 2020). "AR has appeared as a possible therapeutic target for AR-positive triple-negative breast cancer (TNBC)." (PMID 33282730, 2020). "In particular, triple-negative breast cancer is the main subtype that is being targeted for the application of an anti-AR therapy, and is being actively investigated." (PMID 32290220, 2020). "Anti-Androgen Receptor (AR) therapy holds promise for a subset of AR expressing triple-negative breast cancer (TNBC) patients." (PMID 32778063, 2020). "Among triple negative breast cancers, those expressing AR are identified as of the “luminal androgen receptor type”, and AR as a possible therapeutic target is under investigation." (PMID 32626651, 2020). "AR has also emerged as a promising therapeutic target, particularly for AR+ triple-negative breast cancers." (PMID 30795773, 2019). "It is of interest that in our study very few patients with triple-negative breast cancer had high AR1 mRNA levels whereas in immunohistochemical studies AR-positivity rates of 12–32% in triple-negative tumours were described." (PMID 31728025, 2019). "Androgen receptor has been shown to be expressed in 12–55% of patients with triple negative breast cancer, although rates vary by study." (PMID 31769425, 2019). "Increasing studies have demonstrated that enzalutamide is a good treatment strategy for triple negative breast cancer (TNBC) as well as CRPC similarly through targeting AR." (PMID 31126320, 2019). "Since transcriptome studies are expensive, some authors proposed an immunohistochemical definition of the luminal-AR subtype of triple-negative breast cancer." (PMID 31888566, 2019). "Lehmann and colleagues identified a subtype of triple-negative breast cancer (TNBC) characterized by the presence of the androgen receptor (AR) and expression of other luminal genes termed the luminal-androgen receptor (LAR) subtype." (PMID 31840050, 2019). "The androgen receptor (AR) is proposed as a therapeutic target for AR-positive advanced triple-negative breast cancer." (PMID 29713287, 2018). "Overexpression of the androgen receptor (AR) characterizes a distinct molecular subset of triple negative breast carcinomas (TNBC)." (PMID 29883487, 2018). "Results from these trials have been varied with better outcomes reported in AR positive triple negative tumors (LAR—luminal AR subtype of triple negative breast cancer)." (PMID 30416486, 2018).
triple-negative breast carcinoma (continued). "Nuclear AR-serine(p)-650 was found to be decreased in triple negative breast cancer however cytoplasmic AR phosphorylation at serine 650 was increased 1.4 fold." (PMID 30416486, 2018). "Another AR antagonist bicalutamide was under investigation in a phase II clinical trial of triple negative breast cancer." (PMID 30416486, 2018). "This is the case also in a triple-negative breast cancer, in which AR appears to drive tumor progression." (PMID 29731997, 2018). "A prospective single center Phase II study of bicalutamide as a treatment for AR-positive metastatic triple-negative breast cancer (mTNBC) patients (clinicaltrials.gov: NCT02348281) is currently open and actively recruiting participants." (PMID 28474005, 2017). "In this study we sought to investigate the prevalence and prognostic value of androgen receptor (AR) status in operable triple-negative breast cancer (TNBC) patients." (PMID 28915596, 2017). "AR suppresses expression of PR-regulated genes in triple negative breast cancer, suggesting negative regulation of AR on Pgr expression." (PMID 29249975, 2017). "Many clinical studies are underway, such as a feasibility study of adjuvant enzalutamide for the treatment of early stage AR-positive triple negative breast cancer (clinicaltrials.gov: NCT02750358)." (PMID 28474005, 2017). "androgen receptor inhibition with MDV3100 significantly radiosensitized triple-negative breast cancer xenografts in mouse models and markedly delayed tumor doubling/tripling time and tumor weight." (PMID 28840192, 2017). "In a series of triple-negative breast cancers, using a cut-off of 10% to determine AR positivity, it was shown that about 20% of patient tumors were positive for AR." (PMID 26797644, 2016). "Given the availability of androgen receptor-targeted and immune therapies for triple-negative breast cancers, determining predictors of these biomarkers is important." (PMID 28721372, 2016). "Enzalutamide has shown activity in the subset of women with advanced triple negative breast cancer whose tumors express the androgen receptor (AR)." (PMID 27252813, 2016). "Collectively the data enhances our understanding of AR function in TNBCs and it provides novel targets for the therapeutic intervention of triple negative breast cancer, which are positive for downstream AR signalling pathway." (PMID 25781993, 2015). "Taken together the data suggests that AR mediated chemopreventive effect can be reversed by AR antagonist like bicalutamide and therefore we propose to use bicalutamide for the treatment of AR positive, triple negative breast cancer." (PMID 25781993, 2015). "Triple-negative breast cancer is a heterogeneous disease, and the basal-like, mesenchymal-like, immune modulatory, and luminal androgen receptor subgroups have been reported." (PMID 25608004, 2015). "Overall, these studies establish the importance of androgens and AR to treat triple-negative breast cancers." (PMID 25072326, 2014). "The role of androgens and AR in triple-negative breast cancer has been controversial for the last half a century, since the first reports of the “hyperandrogenic” theory." (PMID 25072326, 2014). "In 160 triple negative breast cancers, mRNA microarray expression profiling was performed, and differences according to androgen receptor status were analyzed." (PMID 24505496, 2014). "We next evaluated the expression of the AR in 16 human samples from triple negative breast cancer patients." (PMID 24779793, 2014). "On these bases, clinical trials (ClinicalTrials.gov) have been established focusing on AR targeting in ER-negative cases, such as triple negative breast cancers (TNBCs)." (PMID 24505496, 2014).
triple-negative breast carcinoma (continued). "MDA-MB-231 triple negative breast cancer cells were infected with LacZ or AR adenovirus, treated with DHT, GTx-027, or bicalutamide, and cell viability was measured." (PMID 25072326, 2014). "Other studies found inverse correlation between AR expression and progression-free survival both in ER positive and triple-negative breast cancers." (PMID 25072326, 2014). "This study aimed to discover new potential mechanisms of chemotherapy with drugs used in the treatment of luminal androgen receptor (LAR)-type triple-negative breast cancer (TNBC)." (PMID 24396484, 2014). "Hormonal status of apocrine carcinomas is found to be basal-like triple negative breast cancer with androgen receptor positivity." (PMID 23864975, 2013). "In one study, it was suggested that there are six distinct groups of triple negative breast cancers based on gene expression profiles: basal-like 1, basal-like 2, immunomodulatory, mesenchymal, mesenchymal stem-like, and luminal androgen receptor." (PMID 23071597, 2012). "AR, which is detected in ER-negative breast cancer, has recently been suggested as a therapeutic target for a subset of triple-negative breast cancers." (PMID 22035181, 2011). "However, in contrast, androgen-receptor signaling can also promote tumor progression under certain conditions, especially in triple-negative breast cancer (TNBC), where AR expression is often associated with more aggressive disease and poorer outcomes." (PMID 40286049, 2025). "Triple-negative breast cancer (TNBC) had the lowest probability of AR + (p < 0.001)." (PMID 36929229, 2023). "In ER-negative BC, AR is expressed in tumors with apocrine differentiation and lower Nottingham grade and may stimulate cellular proliferation in triple negative breast cancer." (PMID 37951051, 2023). "Furthermore, CDK4/6 inhibitors have been reported to arrest the cell cycle via a hormone-receptor-independent mechanism in the luminal androgen receptor type of triple-negative breast cancer." (PMID 37158934, 2023). "Moreover, several studies that suggested the formation of GR/AR heterodimers have also been reported, and we also report on the interaction of AR and GR in triple-negative breast cancer." (PMID 37435453, 2022). "Androgen receptor (AR) is one of the predominant nuclear hormone receptors in invasive breast cancer and can be explored as a biomarker of response for targeted anti-androgen therapy, especially in the setting of triple negative breast cancer (TNBC)." (PMID 36405944, 2022). "Androgen receptor (AR) is a potential therapeutic target in triple-negative breast cancer (TNBC)." (PMID 36178912, 2022). "In triple-negative breast cancer (TNBC) patients, high HOTAIR expression in tumor tissues is strongly correlated with lymph node metastasis, and it is directly associated with the androgen receptor (AR)." (PMID 33540611, 2021). "TGF-β inhibitors may play an important role in chemotherapy or androgen receptor blockade in triple-negative breast cancer." (PMID 34644733, 2021). "Additionally, another member of the SHR family, androgen receptor (AR), is also gaining importance, specifically in the field of triple negative breast cancer." (PMID 33777765, 2021). "Published studies on androgen receptor immunoreactivity in triple-negative breast cancer." (PMID 32697770, 2020). "In conclusion, this study preliminarily confirmed in vitro that Bicalutamide can inhibit the proliferation and invasion of triple-negative breast cancer by inhibiting the androgen receptor signaling pathway, which is related to the down-regulation of cyclinD1, mmp-2, and mmp-9 related proteins." (PMID 32332626, 2020). "AR may also play an important role in luminal androgen receptor (LAR) subtype of triple negative breast cancer." (PMID 31847455, 2019). "We identified an AR+ FOXA1+ CK14– subgroup of triple-negative FMCs that might correspond to the luminal-AR subgroup of human triple-negative breast cancers." (PMID 31888566, 2019).
triple-negative breast carcinoma (continued). "We address the challenge of extracting gene signatures from transcriptomic data of prostate adenocarcinoma (PRAD) and breast invasive carcinoma (BRCA) samples, particularly estrogen positive (ER+), and androgen positive (AR+) triple-negative breast cancer (TNBC), using sparse logistic regression." (PMID 31238876, 2019). "The non-basal-like subtype of triple-negative FMCs that coexpresses AR and FOXA1 (the AR+ FOXA1+ CK14– subgroup) could represent the equivalent of the luminal-AR subgroup of human triple-negative breast cancer." (PMID 31888566, 2019). "These discrepant findings might result from the heterogeneity of triple-negative breast cancers (TNBCs), which comprise at least “luminal-Androgen Receptor” and “basal-like” subtypes according to gene expression studies." (PMID 30630524, 2019). "Recent investigations have demonstrated that high AR expression was significantly associated with worse local recurrence-free survival after radiation therapy, which is known to induce DNA damage, and AR can be as a mediator of radioresistance in triple negative breast cancer." (PMID 31151151, 2019). "Moreover, AR stimulates cellular proliferation in triple negative breast cancer (ERα –, PgR –, and HER-2-Neu –)." (PMID 30210453, 2018). "Studies have shown it to antagonize estrogen receptor alpha (ERα) DNA binding, thereby preventing pro-proliferative gene transcription; whilst others have demonstrated AR to take on the mantle of a pseudo ERα particularly in the setting of triple negative breast cancer." (PMID 30416486, 2018). "Recently, it has reported that androgen receptor may be the therapeutic target of androgen-driven triple-negative breast cancer patients, and anti-androgens, widely used to treat metastatic CRPC, can be used for TNBC treatment." (PMID 29934599, 2018). "AR supports anchorage independent growth in triple negative breast cancer." (PMID 30416486, 2018). "Importantly, AR has already been demonstrated as a promising target for antiandrogen therapies in the most aggressive triple-negative breast cancer." (PMID 28551687, 2017). "The knowledge of ARs may be the basis for AR-targeted therapies of androgenic disorders in women, including malignancy, as it has recently been demonstrated for triple-negative breast cancer." (PMID 28551687, 2017). "Moreover, androgen receptor (AR) is expressed in approximately 70 to 90% of invasive breast carcinomas, which has prognostic relevance in basal-like cancers and in triple-negative breast cancers." (PMID 27746764, 2016). "Triple-negative breast cancer (TNBC) patients testing positive for androgen receptor (AR) expression are thought to be chemotherapy resistant, similar to other hormone receptor-positive breast cancers; however, this has not been substantially validated in the clinic." (PMID 26757422, 2016). "The trial enrolled 118 women with AR-positive triple negative breast cancer." (PMID 27252813, 2016). "However, AR is expressed in approximately 70–90% of invasive breast carcinomas, which has prognostic relevance in basal-like cancers and in triple-negative breast cancers." (PMID 27746764, 2016). "This suggests a connection between androgens and breast carcinogenesis, and AR may be useful as a therapeutic target for triple-negative breast cancers." (PMID 26039245, 2015). "Androgen receptor has been associated with triple negative breast cancer pathogenesis, but its role in the different subtypes has not been clearly defined." (PMID 24505496, 2014). "Although the natural history of IAC may be less aggressive than some basal triple negative breast cancers (TNBCs), often with lower proliferation indices, clinical management remains guided by multidisciplinary assessment and growing interest in AR targeted approaches." (PMID 41245818, 2025).